ADRB3 (adrenoceptor beta 3)
Description:
G protein-coupled receptor for catecholamines that couples to both G(s) and G(i) proteins, leading to either activation or inhibition of adenylate cyclase and cAMP-dependent pathway, respectively. The rank order of potency for physiological agonists is norepinephrine > epinephrine. Involved in the regulation of thermogenesis and lipolysis in brown and white adipose tissue, after coupling to G(s) proteins and stimulation of the cAMP-PKA axis (By similarity). Also activates lipolytic process by coupling to G(i) proteins and consequent initiation of the ERK1/2 MAP kinase cascade. Participates in relaxation of the blood vessels and the urinary bladder. Also mediates negative inotropic effects in cardiomyocytes through activation of an NO synthase pathway and subsequent increase in cGMP levels, possibly involving G(i/o) protein-mediated coupling.
Synonyms: BETA3AR
Tractability: Small molecule: an approved drug acts on it; a structure with a bound ligand is known; a high-quality ligand is known; it belongs to a druggable protein family. Antibody: its Gene Ontology location is reachable by antibodies, with high confidence; UniProt places it where antibodies can reach, with medium confidence; UniProt predicts a signal peptide or a membrane-spanning region. PROTAC: a small molecule that binds it is known.
Target class: Small molecule receptor (family A GPCR); Adrenergic receptor; Monoamine receptor; Membrane receptor; Family A G protein-coupled receptor
Chemical probes: BI-2800 (high quality)
Safety:
Unwanted effects reported when the protein is acted on. In parentheses: how it was acted on, where the effect was seen, and who reports it.
weight gain (source: ClinPGx)
Gene: Protein-coding gene on chromosome 8 (37,962,990 to 37,966,599, reverse strand). Ensembl gene ENSG00000188778.
Subcellular location: Cell membrane
Subcellular location (Human Protein Atlas): Basal body; Vesicles
Pathways (Reactome):
Signal Transduction: Adrenoceptors; G alpha (s) signalling events
Gene Ontology:
Molecular function: beta-adrenergic receptor activity; beta3-adrenergic receptor activity; G protein activity; norepinephrine binding; protein binding; protein homodimerization activity; epinephrine binding; adrenergic receptor activity; G protein-coupled receptor activity
Biological process: adenylate cyclase-activating adrenergic receptor signaling pathway; adenylate cyclase-inhibiting G protein-coupled receptor signaling pathway; negative regulation of cardiac muscle contraction; negative regulation of G protein-coupled receptor signaling pathway; negative regulation of smooth muscle contraction; positive regulation of ERK1 and ERK2 cascade; positive regulation of MAPK cascade; receptor-mediated endocytosis; adenylate cyclase-inhibiting adrenergic receptor signaling pathway; adenylate cyclase-modulating G protein-coupled receptor signaling pathway; carbohydrate metabolic process; energy reserve metabolic process; G protein-coupled receptor signaling pathway, coupled to cyclic nucleotide second messenger; generation of precursor metabolites and energy; norepinephrine-epinephrine-mediated vasodilation involved in regulation of systemic arterial blood pressure; positive regulation of cold-induced thermogenesis; positive regulation of lipid catabolic process; adenylate cyclase-activating G protein-coupled receptor signaling pathway; eating behavior; G protein-coupled receptor signaling pathway
Cellular component: plasma membrane; receptor complex; membrane
Genetic constraint (gnomAD): Loss-of-function variants: 33 observed, 19.6 expected, observed/expected ratio (o/e) 1.68, 90% interval 1.25 to 1.95. The synonymous counts are far from expectation, so gnomAD's model fits this gene poorly and the ratio says little. Missense variants: 592 observed, 498.31 expected, observed/expected ratio (o/e) 1.19, 90% interval 1.11 to 1.27. Synonymous variants: 284 observed, 232.63 expected, observed/expected ratio (o/e) 1.22, 90% interval 1.11 to 1.35.
Homologues: Orthologues: chimpanzee ADRB3 (98% identical), macaque ADRB3 (88% identical), pig ADRB3 (83% identical), rabbit ADRB3 (83% identical), dog ADRB3 (83% identical), mouse Adrb3 (78% identical), rat Adrb3 (78% identical), zebrafish adrb3a (44% identical), zebrafish adrb3b (39% identical), Caenorhabditis elegans ser-5 (24% identical). Paralogues in human: ADRB1 (48% identical), ADRB2 (42% identical), ADRA1B (33% identical), ADRA1D (33% identical), ADRA1A (30% identical), ADRA2B (26% identical), DRD2 (26% identical), ADRA2A (26% identical), ADRA2C (26% identical), GPR101 (19% identical), OR56A3 (14% identical), OR56A4 (13% identical), and 6 more.
Diseases named in the same sentence as ADRB3 in open-access papers:
ADRB3 is named in the same sentence as 150 diseases in open-access papers, as found by Europe PMC text mining. Sharing a sentence is not in itself a finding about the gene and the disease. The quoted sentences say what the papers report.
Obesity (152 papers, 2004 to 2026). Accumulation of substantial excess body fat. "Nevertheless, β3-ARs contribute to basal lipolysis and systemic metabolic regulation and variants in adrenoceptor beta 3 gene ADRB3 are associated with obesity and insulin resistance." (PMID 41596403, 2026). "In the study of women with breast cancer, it was observed that homozygous individuals carrying the ADRB3 wild-type allele exhibited significantly higher mean visceral fat levels compared to those with the variant allele, indicating a greater degree of obesity." (PMID 38397196, 2024). "The role of the β3-ARs in human energy metabolism is supported by clinical trials, reporting associations between specific polymorphisms in the human ADRB3 gene (the gene encoding the β3-AR) and higher rates of obesity, insulin resistance, and diabetes." (PMID 37959362, 2023). "On the other hand, ADRB2 variants were linked to insulin resistance, hyperleptinemia, obesity, and T2D, while ADRB3 variants have been associated with dyslipidaemia, obesity, and MetS." (PMID 37512517, 2023). "Aberrant methylation of other genes has also been linked to obesity, such as the beta-3 adrenoceptor gene (ADRB3) and the insulin-like growth factor-2 gene (ILGF2)." (PMID 37899888, 2023). "Here, the prevalence of ADRB3 Trp64Arg polymorphism and the effect of this polymorphism on obesity‐related indicators are described, taking into account major lifestyle‐related factors in a Japanese rural population." (PMID 35388349, 2022). "For obesity (ADRB3 and FTO genes) the lowest average risk score was calculated for the Parakanã (0.188) and the highest for the Araweté group (0.413)." (PMID 35560161, 2022). "DNAm levels were measured in 61 men with familial hypercholesterolemia (FH) and 30 men with severe obesity, and common ADRB3 polymorphisms were genotyped." (PMID 36397166, 2022). "Previous epidemiological studies have shown mixed results on the relationship between the ADRB3 Trp64Arg polymorphism and obesity and its related parameters." (PMID 35388349, 2022). "Second, only the ADRB3 gene polymorphism was analyzed as a candidate gene for overweight and obesity in this relatively small genome cohort." (PMID 35388349, 2022). "In the present study, the association of ADRB3 gene polymorphisms and lifestyle‐related factors with obesity‐related parameters was examined in a multivariate model." (PMID 35388349, 2022). "It appears that modifications in diet and lifestyle can overcome the effect of the ADRB3 Trp64Arg gene polymorphism on overweight and obesity." (PMID 35388349, 2022). "A polymorphism in the ADRB3 gene (Trp64Arg) has been associated with obesity, insulin resistance, and hypertension." (PMID 34347822, 2021). "Previous studies examined the relationships among the ADRB3 polymorphism, obesity, insulin resistance, and hypertension." (PMID 34347822, 2021). "Researches showed that ADRB3 polymorphic variants are associated with many diseases, such as cardiovascular diseases, obesity, diabetes, and other disorders." (PMID 34512548, 2021). "A role for the β3-ARs in human energy metabolism is supported by clinical trials reporting associations between specific polymorphisms in the human ADRB3 gene and higher rates of obesity, insulin resistance, and diabetes." (PMID 34100382, 2021). "In conclusion, the results of this meta-analysis evaluating the genetic impact of the ADRB3 rs4994 polymorphism on the risk of overweight/obesity among children and adolescents are reassuring." (PMID 32008426, 2020). "It is still unable to exclude the likelihood that other functional polymorphisms of the ADRB3 gene also contribute to the risk of overweight/obesity." (PMID 32008426, 2020). "In this study and our previous study of ADRB3 SNP showed that the association between genetic risk factor and obesity were found in rural." (PMID 31915589, 2020).
Obesity (continued). "To date, many epidemiological assessments were completed to quantitatively determine the association between the ADRB3 rs4994 polymorphism and risk of childhood and adolescent overweight/obesity." (PMID 32008426, 2020). "There is still uncertainty regarding the genetic impact of the ADRB3 rs4994 polymorphism on the risk of childhood and adolescent overweight/obesity despite previous case–control studies." (PMID 32008426, 2020). "Given the significance of this ADRB3 polymorphism, it is necessary to quantitatively assess the strength of its relationship with overweight/obesity risk." (PMID 32008426, 2020). "Among them, a number of studies have focused on a common ADRB3 rs4994 polymorphism (T190C, Trp64Arg) to investigate the genetic effect on the development of obesity." (PMID 31929840, 2019). "Ensuing DNA methylation of the promoter leads to diminished Adrb3 expression and blockade of thermogenesis and lipolysis or beiging, which in turn facilitates obesity and associated pathological states such as insulin resistance and dyslipidemia." (PMID 31387996, 2019). "Hypermethylation of the ADRB3 gene promoter in blood cells and visceral fat tissue has previously been associated with the development of obesity and metabolic complications in men." (PMID 30954083, 2019). "This is the first study to report the relationship between ADRB1 and ADRB3 gene polymorphism and obesity-related phenotypes in the Saudi population." (PMID 29587766, 2018). "The results of this study have shown a significant association between the Trp64Arg polymorphism in ADRB3 gene and the development of overweight and obesity in Saudi populations." (PMID 29587766, 2018). "We scanned for the polymorphism of Arg389Gly (rs1801253) in ADRB1 and Trp64Arg (rs4994) in ADRB3 genes in Saudi population to determine association, if any, of these polymorphisms with obesity and related disorders." (PMID 29587766, 2018). "CPT1B transports free acyl groups into mitochondria for oxidation, and ADRB3 triggers lipolysis in adipocytes, and their respective polymorphisms E531K and W64R have been identified as indicators of obesity in population studies." (PMID 24905907, 2014). "Genes encoding UCP1 (UCP1) and ADRB3 (ADRB3) have been studied to elucidate genetic variations accounting for the susceptibility to obesity." (PMID 24086366, 2013). "As an important theme regarding the ADRB3 polymorphism, further investigation into the relationship between ADRB3 and the effects of exercise on obesity is warranted." (PMID 22550477, 2012). "There were meta-analysis studies concerning the ADRB3 polymorphism and obesity which indicated that Arg/Arg genotype led to increased body weight." (PMID 22550477, 2012). "One variant in the ADRB3 gene, the Trp64Arg (rs 4994) in the first cytoplasmic region (Uniprot accession p13945), was reported to be associated with obesity, although others have contradict this finding." (PMID 21619577, 2011). "Our work was the first in studying Trp64Arg polymorphism among ethnic Kyrgyz people, where we found an association of this ADRB3 gene polymorphism with components of MS, such as obesity, AO, and decreased HDL-C level." (PMID 21992420, 2011). "It has been reported that the ADRB3 Trp64Arg gene polymorphism was associated with obesity in Korean middle-aged women." (PMID 21619577, 2011). "In this study we determined the prevalence of obesity and metabolic syndrome among urban and rural Balinese, and studied the association of ADRB3 Trp64Arg polymorphism with obesity and MetS." (PMID 21619577, 2011). "We found that the Arg64 allele of the ADRB3 Trp64Arg gene polymorphism was associated with obesity in rural female subjects." (PMID 21619577, 2011). "Our results indicated an association of the ADRB3 Trp64Arg gene polymorphism with obesity in the rural female." (PMID 21619577, 2011). "Arg64 allele of the ADRB3 gene in the studied group has an association with MS components such as obesity, AO and decreased HDL-C level." (PMID 21992420, 2011).
Obesity (continued). "We also examined the frequency of the ADRB3 Trp64Arg gene polymorphism, and did a preliminary study to look for the association of this variant with obesity and MetS." (PMID 21619577, 2011). "In this pilot study, we looked for the association of the Arg64 minor allele of the ADRB3 Trp64Arg gene polymorphism with obesity, defined by high BMI (> 25 kg/m2) and WC (≥ 80 cm for female and ≥ 90 cm for male, respectively)." (PMID 21619577, 2011). "Many genes are suspected to be associated with obesity, and recently the β3-adrenergic receptor gene (ADRB3) has become the center of attention." (PMID 16276029, 2005). "The results of the multiple logistic regression analysis showing that the presence of the polymorphism of ADRB3 increases the risk of obesity in the 4th quartile alone also suggests interaction between high energy intake and the polymorphism of ADRB3." (PMID 16276029, 2005). "Many studies have demonstrated that the polymorphism of ADRB3 is associated with obesity, but few studies have shown that it is possible to prevent or treat obesity and its complications in persons with the polymorphism." (PMID 16276029, 2005). "The Trp64Arg polymorphism of ADRB3 warrants consideration, along with other polymorphisms involved in the development of obesity, for tailor-made prevention of obesity." (PMID 16276029, 2005). "Only the presence of the polymorphism of ADRB3 was associated with increased risk of obesity (adjusted OR=3.37, 95% CI=1.12-10.16)." (PMID 16276029, 2005). "Further studies investigating the interaction between the Trp64Arg polymorphism of ADRB3 and other polymorphisms involved in the development of obesity, will be needed." (PMID 16276029, 2005). "The ADRB3 rs4994 polymorphism could significantly increase the risk of childhood and adolescent overweight/obesity, especially for East Asia's population." (PMID 41082226, 2025). "Moreover, ADRB3 gene mutations were associated with an increased risk of obesity and diabetes, insulin resistance and nonalcoholic fatty liver disease in the obese condition." (PMID 38397396, 2024). "The correlation of rs4994 (ADRB3 gene) with obesity may be mediated by the impact of this polymorphism on adipokines." (PMID 36983642, 2023). "Additionally, the ADRB3 gene has surfaced as an important gene associated with obesity/dyslipidemia as it encodes for a beta-adrenergic receptor found on the surface of adipocytes and is important regulator of lipolysis." (PMID 36615885, 2023). "Collectively, these results suggest that upregulation of adipocyte Mettl3, Mettl14, and m6A methylation of Atgl, Cgi‐58, Adrb2, and Adrb3 transcripts causes, at least in part, adipose catecholamine resistance, lipolysis suppression, adipose expansion, and metabolic disorders in obesity." (PMID 37526326, 2023). "Moreover, mutations in the gene ADRB3 have been correlated with insulin resistance, increased risk of obesity and diabetes, and nonalcoholic fatty liver disease in obese individuals." (PMID 37959362, 2023). "Several variants of the ADRB3 gene are associated with the development of obesity and T2DM." (PMID 36983642, 2023). "Moreover, an SNP (rs4994) in the ADRB3 gene has been associated with obesity in different populations." (PMID 36532520, 2022). "The β3‐adrenergic receptor (ADRB3) gene polymorphism has been implicated in obesity." (PMID 35388349, 2022). "ADRB3 expression levels in adipocytes were downregulated before the onset of obesity, indicating that reduced ADRB3 expression might be the cause of obesity." (PMID 36532520, 2022). "Therefore, the contribution of ADRB3 Trp64Arg polymorphism to obesity‐related indicators was investigated, taking into account the lifestyle‐related factors in a Japanese rural population." (PMID 35388349, 2022). "However, this meta-analysis shows that the C allele of this polymorphism in the ADRB3 gene is a risk factor for overweight/obesity only in children and adolescents from East Asia." (PMID 32008426, 2020).